LEPR (leptin receptor)
Diseases named in the same sentence as LEPR in open-access papers (continued):
Sharing a sentence is not in itself a finding about the gene and the disease.
Obesity (continued). "This animal model presents leptin receptor deficiency, and has served as a rodent model for obesity and type 2 diabetes for more than 40 years." (PMID 30205562, 2018). "The role of diet in modulating the association between LEPR gene variants and overweight/obesity was examined through logistic regression analysis on food consumption in a well-characterized cohort of children and adolescents in Salvador, Bahia, Brazil." (PMID 30126176, 2018). "For genetic obesity models, three studies used leptin receptor-deficient (db/db) mice and one study used Otsuka Long Evans Tokushima Fatty (OLEFT) rats." (PMID 29861768, 2018). "Variants of the LEPR gene influencing obesity and obesity-related traits have been studied in children and adolescents in India, Spain, Mexico with the variants rs1137101, rs1137100, and rs8179183 being the most commonly studied." (PMID 30126176, 2018). "Other obese models such as the ob/ob and db/db, have a defect in leptin or the leptin receptor, which prevent leptin regulation on obesity-associated signaling pathways in cancer." (PMID 30567335, 2018). "A study performed on white children assessing 223, 492, and 1019 leptin receptor gene polymorphisms concluded that the most frequent combinations in children with obesity were AG/GG/GA, AG/GG/GG, and AA/GG/GA." (PMID 30338250, 2018). "Leptin receptor deficiency evokes hyperphagia, leading to severe obesity, glucose intolerance, and hyperglycemia." (PMID 29323138, 2018). "The results of this study offer new insights into the interrelationships between the genetic variants of LEPR, and dietary intake and obesity." (PMID 30126176, 2018). "Regarding the analyses run for the food groups, an interaction was found between daily soft drinks/artificial juices intake frequency and LEPR gene variant rs1137100 (interaction p = 0.019) relative to overweight/obesity." (PMID 30126176, 2018). "The gene for the leptin receptor (LEPR), which is implicated to both cardiac hypertrophy and cardioprotection in obesity, was upregulated." (PMID 29556499, 2018). "Leptin receptor (OB-R) can induce cardiac disorders and also is linked with obesity development, which leads to obesity risk." (PMID 30013563, 2018). "The disruption of LEPR and leptin deficiency results in severe early-onset hyperphagic obesity with rapid weight increase during the first few months of life." (PMID 30442103, 2018). "Many candidate gene and genome-wide association studies (GWAS) have been carried out where LEP and LEPR polymorphisms have been investigated for their role in measures of adiposity, obesity and its sequelae." (PMID 30121879, 2018). "Leptin- (ob/ob) or LEPR-deficient (db/db) mice for instance are morbidly obese due to uncontrolled food intake, whereas animals deficient for IL-6 develop mature onset obesity." (PMID 30224299, 2018). "The levels of TRPV1 mRNA in BAT and WAT are reduced in HFD-induced obesity and leptin receptor deficient mice suggesting possible involvement in the development of obesity." (PMID 30108548, 2018). "Several studies have demonstrated the association between the LEPR gene, SNVs, and overweightness/obesity in children and adolescents, but other results are discordant." (PMID 30126176, 2018). "Other studies have demonstrated increased mTOR/S6K1 activation in the transgenic Zucker obese (ZO) rat, a model of overnutrition and obesity which carries a mutation of the leptin receptor and develops INS resistance and glucose intolerance." (PMID 30116740, 2018). "Mutations in human KSR2, MC4R, LEP and LEPR have been described as monogenic causes of obesity, confirming that this screen has relevance to human monogenic obesity disorders." (PMID 30563851, 2018). "In both the LEP and LEPR genes, homozygous mutations have been described that derive in extreme obesity." (PMID 28771179, 2017).
Obesity (continued). "In the LEPR gene, different SNPs conferring increased susceptibility to common forms of obesity have been identified in adults, families and children with different ethnic backgrounds." (PMID 28771179, 2017). "Inborn errors of the leptin/leptin receptor system in humans are rare conditions caused by mutations in either the leptin or the leptin receptor gene that lead to early onset extreme obesity." (PMID 28007844, 2017). "With all this in mind, the present study was undertaken with the aim of elucidating the possible association regarding LEPR variants in the setting or development of obesity in children." (PMID 28771179, 2017). "First, this in vitro study only dealt with intrinsic diaphragmatic contractility and the relevance of the leptin receptor-deficient rat model for Type 2 diabetes mellitus and obesity is still a matter of discussion." (PMID 28328996, 2017). "The LEPR D1S200 17 allele was associated with increased susceptibility to obesity and increased BMI, WC, and WHR in Brazilian individuals." (PMID 28615046, 2017). "The analysis of CNVs in six regions corresponded to five genes previously associated with obesity, LEPR (intron 2 and intron 3), NEGR1, ARHGEF4, CPXCR1, and INS, and four intergenic regions (1p36.33b, 12q15c, 15q21.1a, and 22q11.21d)." (PMID 28428959, 2017). "We assessed the association of 28 LEPR polymorphisms with body mass index (BMI) and their relationship with obesity-related phenotypes, inflammation and cardiovascular disease risk biomarkers." (PMID 28771179, 2017). "Here, we focus on leptin receptor nonsense variants causing obesity, namely the human W31X, murine Y333X and rat Y763X mutations, and explored their susceptibilities to aminoglycoside and PTC124 mediated translational read-through in vitro." (PMID 28432296, 2017). "Obesity in the Zucker rat is inherited as an autosomal recessive trait caused by a mutation in the leptin receptor gene (fa)." (PMID 28704522, 2017). "In mice, mutation of both leptin and the leptin receptor is associated with obesity and disturbed glucose homeostasis." (PMID 28441764, 2017). "Hyperphagia, obesity and defective locomotion were observed in mice with deficiency of LepR or its key signaling molecule STAT3 in the LH or VTA on chow diet." (PMID 28560316, 2017). "LEPR has diverse roles in metabolism, appetite and bone formation with obesity linked to both elevated levels of leptin and increased cancer incidence." (PMID 29212170, 2017). "While leptin receptor-deficient mice showed impaired NK cell activity, leptin receptor expression was upregulated in rats with diet-induced obesity, apparently to compensate for decreased downstream signalling." (PMID 29073286, 2017). "Zucker (fatty) rats have a spontaneous mutation in the leptin receptor (LeprfaSte) that causes obesity and other phenotypes characteristic of metabolic syndrome on a chow diet." (PMID 29211750, 2017). "Mutated LEPR plays a crucial role in the pathogenesis of obesity and/or diabetes in leptin receptor-deficient db/db mice, Zucker fatty (fa/fa) rats, and Koletsky rats." (PMID 28596541, 2017). "The current studies demonstrate that by comparison to lean controls, CEACAM1 level is reduced in the liver of age- and sex-matched obese human subjects and in three rat models of obesity resulting from null mutation of leptin receptor." (PMID 28396653, 2017). "The present study investigated how DJB procedure affected metabolic homeostasis and obesity in db/db mice, a leptin receptor deficiency T2DM animal model." (PMID 29238655, 2017). "We created whole-body tamoxifen-inducible leptin receptor (LepR)-deficient mice (Ubc-CreERT2LepRloxP/loxP) as a novel model of acute obesity." (PMID 27003683, 2016). "Genetic variability in the LEP and LEPR gene was previously associated with susceptibility to obesity and obesity-related metabolic diseases." (PMID 28051281, 2016).
Obesity (continued). "Many available models of obesity are derived from selective crossing between rats comprising one out of the two most significant mutations in leptin receptor (i.e. fa and cp)." (PMID 26936157, 2016). "In particular, the LEPR Q223R polymorphism is significantly associated to obesity in women treated with atypical antipsychotic drugs." (PMID 27673331, 2016). "The studies performed on French Caucasians, Finish, and Japanese45 pointed out the association of LEPR 223 gene polymorphism with different markers of obesity and also with diabetes mellitus." (PMID 27015185, 2016). "Caloric restriction also improves obesity and reverses deficits in leptin receptor protein and signaling associated with diet-induced obesity." (PMID 26881095, 2016). "Constitutive leptin receptor (LepR) signalling mutant models (db/db and ob/ob mice, fa/fa rats) develop obesity through germ line loss of leptin signalling." (PMID 27003683, 2016). "The interest in LEP and LEPR as susceptibility genes for human obesity led to the identification of several common polymorphisms, among which LEPR –2548 G/A and LEPR Gln223Arg are of major importance." (PMID 27015185, 2016). "Here we show that neuronal Bardet-Biedl syndrome (BBS) proteins, encoded by genes that cause obesity when mutated, govern energy homeostasis through the control of cell surface expression of the leptin receptor." (PMID 26926121, 2016). "Other genetic studies have confirmed biological predisposition to overeating and weight gain, indicating that genetic polymorphism of dopamine D2 receptor and leptin receptor genes are involved in obesity and craving for food." (PMID 27036220, 2016). "Several LEPR mutations have been described in patients with early-onset of severe obesity and hyperphagic eating behavior." (PMID 28096764, 2016). "Since LEPR is of functional importance for the risk factor of OA-obesity, numerous investigations regarding the association between LEPR SNPs with obesity have been extensively carried out." (PMID 27457563, 2016). "Zucker diabetic fatty (ZDF) rats with a missense mutation (fatty, fa) in the leptin receptor gene (LEPR) develop obesity, insulin resistance, and T2D." (PMID 27418144, 2016). "Acute LepR deficiency dramatically increased beta cell mass in response to obesity, by 3.7-fold at 5 weeks." (PMID 27003683, 2016). "In animal studies, maternal diet restriction has been associated with subsequent obesity at a few months of age as well as reduced birth weight of the offspring and reduced expression of LEPR." (PMID 27330572, 2016). "According to a multivariate analysis, the highest risk of developing obesity was owned by the children with AG+GG genotypes of the LEPR 223 gene, and GA + AA for the LEPR 1019 gene." (PMID 27015185, 2016). "Several LEPR mutations and polymorphisms have been described in patients with early onset severe obesity and hyperphagic eating behavior; however, some contradictory findings have also been reported." (PMID 28096764, 2016). "Our results suggest that dietary fat intake modifies the effect of polymorphisms at the APOA5 and LEPR genes on serum triglycerides, cholesterol levels and obesity in young subjects." (PMID 26365669, 2015). "Human mutations in either the leptin (obese, or ob) or the leptin receptor (LepR) gene lead to severe obesity from an early age." (PMID 26413468, 2015). "It is now two decades since the discovery of defects in Lep and Lepr in the mouse models ob/ob and db/db respectively led to the discovery of the first monogenic obesity syndromes, leptin and leptin receptor deficiency, in humans." (PMID 26120850, 2015). "The polymorphisms in leptin (LEP G-2548A) and leptin-receptor (LEPR Gln223Arg) seem to influence obesity and lipid metabolism among others." (PMID 26064921, 2015). "In a more recent study, 8 other patients with severe early onset obesity with homozygous or compound heterozygous mutations in LEPR were identified." (PMID 25825681, 2015).
Obesity (continued). "Our results suggest that dietary fat intake modifies the effect of APOA5 and LEPR polymorphisms on serum triglycerides, cholesterol levels and obesity in young subjects." (PMID 26365669, 2015). "The db/db mouse model, which is characterized by deficient leptin receptor activity, is known to cause deleterious changes in various tissues triggered by hyperglycemia, dyslipidemia, obesity, insulin resistance, and advanced glycation." (PMID 25789330, 2015). "The C57BL/6J-db/db mouse is a genetic animal model of obesity and type 2 diabetes and is a useful model to study the pathogenesis of obesity-induced insulin resistance when leptin receptor activity is deficient." (PMID 26507490, 2015). "The analysis for LEPR polymorphism, using chi-square, showed association between BMI ≥ 25 kg/m2 and obesity with genotype and phenotype frequencies." (PMID 26064921, 2015). "Db/db mice possessing a mutation in the leptin receptor demonstrate an increased propensity for diet-induced obesity and diabetes via congenital hyperphagia." (PMID 26834700, 2015). "The role of leptin on pancreatic cancer growth in vivo had previously been reported through experiments utilizing the LepDB (long form leptin receptor deficient) and LepOB (ligand deficient) mice that inherently develop obesity." (PMID 25919692, 2015). "The leptin (LEP) and leptin-receptor (LEPR) genes have been studied to find gene variants potentially related to the pathophysiology of obesity, T2DM, and their associated complications." (PMID 26064921, 2015). "While there are a variety of pathways that can lead to obesity, perhaps the best characterized are the aberrant feeding behaviors associated with alterations in the leptin/leptin receptor pathway." (PMID 25856311, 2015). "Defective leptin signaling, due to either leptin deficiency or mutations in the leptin receptor, leads to the development of obesity." (PMID 26493717, 2015). "A homozygous loss-of-function mutation in the leptin receptor (the db mutation) causes hyperphagia and obesity, leading to diabetes in mice." (PMID 26236282, 2015). "It should be noted that the knockout of the Stat3 gene or the mutation of STAT3-interacting residues Tyr1138 in leptin receptor led to the obesity and hyperphagia." (PMID 28031898, 2015). "Mutations in leptin, leptin receptor, and the central melanocortin system are the most common mutations in the monogenic form of obesity in humans." (PMID 26236282, 2015). "Zucker fatty rats (ZUC- LeprfaSte (RGD ID: 629462) referred to as ZUC or the ZUC strain in this paper) exhibit extreme obesity when they are homozygous for the recessive fatty mutation in the leptin receptor (LeprfaSte)." (PMID 24498189, 2014). "In particular, in the genetic model of db/db mice, diabetes and obesity are the result of a deficit in the leptin receptor, while the beta-cytotoxic agent streptozotocin causes a severe hyperglycemic/hypoinsulinemic state." (PMID 25093405, 2014). "Although this is the first study describing the effect of central leptin on TH expression in a diet-induced obesity model, our results coincide with findings of leptin-deficient ob/ob mice and leptin receptor-deficient obese Zucker rats." (PMID 24498181, 2014). "The obesity mutation is a recessive trait, designated fak, which is a nonsense mutation of the leptin receptor gene." (PMID 24512213, 2014). "Obesity is the primary phenotypic manifestation observed in the various leptin- and leptin receptor-deficient rodents, but they also display some T2DM-like characteristics such as hyperglycemia, glucose intolerance, and elevated plasma insulin." (PMID 24809394, 2014). "Studies in human populations and mouse models of disease have linked the common leptin receptor Q223R mutation to obesity, multiple forms of cancer, adverse drug reactions, and susceptibility to enteric and respiratory infections." (PMID 24743494, 2014).
Obesity (continued). "In contrast, in ZF rats, a model of obesity with a mutation in the leptin receptor gene, basal insulin secretion was already high compared with the control, but significant GIIS occurred." (PMID 25373904, 2014). "The db/db mouse is a model of obesity, diabetes, and dyslipidemia, in which leptin receptor activity is deficient because the mice are homozygous for a point mutation in the leptin receptor gene." (PMID 24555693, 2014). "To explore the interactive effects of obesity and the LEPR gene polymorphisms on hypertension, we analyzed the relation between polymorphisms (Lys109Arg, Gln223Arg and Lys656Asn) and hypertension by stratification analyses." (PMID 24522342, 2014). "ZF rats, which bear a loss-of-function leptin receptor gene, develop obesity, dyslipidemia and insulin resistance due to hyperphagia." (PMID 25105869, 2014). "In the assessment of obesity, whole-exome sequencing has identified sequence variants in the leptin receptor gene, in the ADCY3 gene and in the BBIP1 gene in patients with Bardet–Biedl syndrome." (PMID 25158045, 2014). "This retention of leptin-mediated inhibitory responses is consistent with the modest level of obesity in Magel2-null mice compared with leptin-deficient Lepob or leptin receptor null Leprdb mice." (PMID 23341784, 2013). "Other genetic models of obesity and diabetes, including the leptin- or leptin receptor-deficient obese mice (ob/ob or db/db), are also more susceptible to alkylation-induced ACF." (PMID 23560112, 2013). "Treatment with the HSL inhibitor was also performed for 2 wk in 6-wk-old Leprdb/Leprdb mice that carry homozygous mutation of the leptin receptor and are genetically prone to obesity and diabetes." (PMID 23431266, 2013). "The db/db mouse which has a G-to-T mutation in the gene coding the leptin receptor develops obesity, insulin resistance, and T2DM spontaneously." (PMID 23844375, 2013). "Mutations in the human leptin gene are associated with hypogonadism and morbid obesity, and mutations in the human leptin receptor gene causes obesity and pituitary dysfunction." (PMID 23533722, 2013). "Interval mapping of body weight QTL shows that the LOD score peak maps upstream of leptin receptor and shows an additive effect suggesting this as a novel mutation and signifying the model as a valuable resource for studies on obesity and metabolic syndrome." (PMID 24204914, 2013). "It is known that mice with deficient leptin receptor (db/db mice) function develop obesity and lack hypothalamic responsiveness to leptin stimulation." (PMID 23554574, 2013). "ZF rats, a rat model of obesity development, develop obesity due to a missense mutation in the extracellular domain of all leptin receptor isoforms." (PMID 27335827, 2013). "Zucker obese (ZO) rat model develops MS characterized by obesity since they are polyphagic due to a mutation in the leptin receptor, insulin resistance, hypertriglyceridemia, and hypertension." (PMID 23691518, 2013). "The obesity mutation is a recessive trait, designated fak, which is a nonsense mutation of the leptin receptor gene resulting in a premature stop codon in the leptin receptor extracellular domain." (PMID 23573411, 2013). "The db/db mouse strain is a well known model of obesity, diabetes, and dyslipidemia, in which leptin receptor activity is deficient (Lepr−/−)." (PMID 23247284, 2012). "Similar to mouse models, mutations in human leptin and/or leptin receptor genes are associated with early-onset childhood obesity." (PMID 23028384, 2012). "The db/db mouse is homozygous for a point mutation in the gene for the leptin receptor, and is used as a model of obesity and diabetes." (PMID 22952896, 2012). "Some studies have been conducted on the leptin receptor and ghrelin gene and the polymorphisms have been associated with development of obesity in Saudis." (PMID 23056045, 2012).